ETFBKMT (electron transfer flavoprotein subunit beta lysine methyltransferase)
Description:
Protein-lysine methyltransferase that selectively trimethylates the flavoprotein ETFB in mitochondria. Thereby, may negatively regulate the function of ETFB in electron transfer from Acyl-CoA dehydrogenases to the main respiratory chain.
Synonyms: ETFB-KMT; C12orf72; METTL20; DKFZp451L235; MGC50559
Tractability: No criterion of Open Targets' tractability assessment is met for any kind of drug.
Gene: Protein-coding gene on chromosome 12 (31,647,160 to 31,673,114, forward strand). Ensembl gene ENSG00000139160.
Subcellular location: Cytoplasm; Mitochondrion matrix
Pathways (Reactome):
Metabolism of proteins: Protein methylation
Gene Ontology:
Molecular function: heat shock protein binding; protein-lysine N-methyltransferase activity
Biological process: negative regulation of fatty acid beta-oxidation
Cellular component: cytoplasm; mitochondrial matrix; mitochondrion; protein-containing complex
Genetic constraint (gnomAD): Loss-of-function variants: 17 observed, 24.86 expected, observed/expected ratio (o/e) 0.68, 90% interval 0.47 to 1.03. The synonymous counts are far from expectation, so gnomAD's model fits this gene poorly and the ratio says little. Missense variants: 293 observed, 321.16 expected, observed/expected ratio (o/e) 0.91, 90% interval 0.83 to 1. Synonymous variants: 84 observed, 114.59 expected, observed/expected ratio (o/e) 0.73, 90% interval 0.61 to 0.88.
Homologues: Orthologues: chimpanzee ETFBKMT (99% identical), macaque ETFBKMT (97% identical), dog ETFBKMT (87% identical), rat Etfbkmt (77% identical), mouse Etfbkmt (77% identical), guinea pig ETFBKMT (71% identical). Paralogues in human: HEMK1 (15% identical), HEMK2 (12% identical).
Diseases named in the same sentence as ETFBKMT in open-access papers:
ETFBKMT is named in the same sentence as 3 diseases in open-access papers, as found by Europe PMC text mining. Sharing a sentence is not in itself a finding about the gene and the disease. The quoted sentences say what the papers report.
Intellectual disability (1 paper, 2023). "Furthermore, seven intellectual disability candidate genes, TM7SF3, STK38L, ARNTL2, ERGIC2, TMTC1, DENND5B and ETFBKMT have been identified." (PMID 37034680, 2023).
neurodevelopmental disorder (2 papers, 2023). A behavioral and cognitive disorder with onset during the developmental period that involves impaired or aberrant development of intellectual, motor, or social functions. "As a result, we identified a dozen candidate genes: TSPAN11 as a potential KS candidate gene, TM7SF3, STK38L, ARNTL2, ERGIC2, TMTC1, DENND5B, and ETFBKMT as candidate genes for the neurodevelopmental disorder, and INTS13, REP15, PPFIBP1, and FAR2 as candidate genes for KS with ID." (PMID 37563198, 2023). "The results identified one potential KS candidate gene (TSPAN11), seven candidate genes for the neurodevelopmental disorder (TM7SF3, STK38L, ARNTL2, ERGIC2, TMTC1, DENND5B, and ETFBKMT), and four candidate genes for KS with ID (INTS13, REP15, PPFIBP1, and FAR2)." (PMID 37034680, 2023).
ETFBKMT also shares sentences with these, for which no sentence is quoted: metabolic disease (1 paper).